RET (ret proto-oncogene)
Diseases named in the same sentence as RET in open-access papers (continued):
Sharing a sentence is not in itself a finding about the gene and the disease.
diverticular disease (3 papers, 2015 to 2023). A complex disorder characterised by mucosal outpouchings (diverticulae) of the colonic wall which can become infected and inflamed leading to diverticulitis, perforation and bleeding. "As myenteric plexus are known to be the main source of GDNF receptor expression, immunopositive signals of RET and GFRα1 were investigated in colonic myenteric ganglia of patients with diverticulosis and DD." (PMID 28152033, 2017). "Myenteric expression of RET dropped down significantly to 53% ± 15% of control values in patients with diverticulosis and to 33% ± 10% of control values in patients with DD, respectively." (PMID 28152033, 2017). "Myenteric immunoreactivity of the receptors GFRα1 and RET was decreased in both asymptomatic diverticulosis and DD patients." (PMID 28152033, 2017). "The mRNA expression of RET exhibited the strongest down-regulation with a drop-down to 43% ± 10% of control values in patients with diverticulosis and 41% ± 7% of control values in patients with DD." (PMID 28152033, 2017). "In patients with diverticulosis the robust neuronal staining of RET was slightly decreased, whereas the surrounding neuropil exhibited a strong reduction in RET immunopositive signals, when compared to controls." (PMID 28152033, 2017). "Confirmatory to mRNA expression, we observed a significant reduction in the myenteric protein expression of both GDNF receptors, GFRα1 and RET and in both patients with asymptomatic diverticulosis and DD, as quantified with fluorescence-immunohistochemistry." (PMID 28152033, 2017). "Furthermore GFRA1 and RET myenteric plexus mRNA expression of patients with diverticulosis and DD was down-regulated, whereas GDNF remained unaltered." (PMID 28152033, 2017). "Although no morphometric alterations of the ENS was found in patients with symptomless diverticulosis, decreased mRNA expression of GDNF and mRNA expression and fluorescence-intensity of its corresponding receptors GFRα1 and RET were found not only in DD but also in asymptomatic diverticulosis." (PMID 28152033, 2017). "Quantitative analysis of immunopositive RET and GFRα1 signals in the myenteric plexus of patients with diverticulosis, DD and controls revealed a significant drop-down in fluorescence intensity of RET to 38% ± 5% for diverticulosis and to 46% ± 4% for DD, when compared to controls." (PMID 28152033, 2017). "Thus, we performed a consensus-based morphometric analysis of the myenteric plexus and investigated the expression levels of GDNF and its receptors GFRα1 and RET in the tunica muscularis and myenteric plexus of patients with diverticulosis, DD, and controls at gene and protein level." (PMID 28152033, 2017). "Samples of tunica muscularis (TM) and laser-microdissected myenteric ganglia from patients with diverticulosis, DD and controls were analyzed for mRNA expression levels of GDNF, GFRA1, and RET by RT-qPCR." (PMID 28152033, 2017). "Although no myenteric morphometric alterations were found in patients with diverticulosis, GDNF, GFRA1 and RET mRNA expression was down-regulated in the TM of patients with diverticulosis as well as DD." (PMID 28152033, 2017). "Since enteric muscle layers and neuronal tissue vary in mRNA expression levels of GDNF and its corresponding receptors, we performed site-specific mRNA expression analysis of RET, GFRA1 and GDNF of RNA isolated from myenteric ganglia of patients with diverticulosis and DD." (PMID 28152033, 2017).
Down syndrome (3 papers, 2013 to 2021). "Overall occurrence of HSCR in Down syndrome is low (∼1%), and the common RET +3 polymorphism is highly associated with HSCR among children with Down syndrome, suggesting that some level of RET dysfunction is required for penetrant disease (49a)." (PMID 23639815, 2013). "Down syndrome patients with HSCR (HSCR-DS) have no RET mutation in the coding sequence but a significantly increased frequency and over-transmission of a hypomorphic T allele in RET at rs2435357 SNP." (PMID 23671607, 2013).
endocrine cancers (3 papers, 2017 to 2022). "Although genetic predisposition is recognized and all cells carry the same mutation in a RET-carrier patient, not all cells in a given tissue undergo tumorigenesis processes and not all mutation carriers will develop endocrine cancers commonly related to MEN 2 phenotype." (PMID 31288802, 2019).
Insulin resistance (3 papers, 2021 to 2025). Increased resistance towards insulin, that is, diminished effectiveness of insulin in reducing blood glucose levels. "The involvement of RET oncogene in the same pathway of insulin signaling explains its role in the molecular pathogenesis of insulin resistance." (PMID 34360895, 2021). "We implemented a combined bioinformatics analysis to retrieve a set of ceRNA networks (LncRNA-RP11-773H22.4, miR-1, miRNA-3163, which is related to insulin resistance and their targeting signaling pathway genes RET, IGF1R, GLUT4, AKT2 and mTOR mRNAs) from public databases." (PMID 34360895, 2021). "There was a highly significant positive correlation between each of the following: LncRNA-RP11-773H22.4, RET, IGF1R, mTOR mRNAs, glycemic control and insulin resistance." (PMID 34360895, 2021). "In particular, STZ-induced insulin resistance in astrocytes reduces endogenous neurotrophic factor expression, including GDNF, and disrupts the IR/IRS-1/Akt signaling pathway, which is part of the downstream cascade activated by GDNF through RET." (PMID 40456763, 2025).
interstitial lung disease (3 papers, 2023 to 2026). A diverse group of lung diseases that affect the lung parenchyma. "We demonstrate that the RET inhibitor pralsetinib (Pral) induces fatal interstitial lung disease by inhibiting FGFR1, not RET, leading to the selective loss of occludin (OCLN)." (PMID 42088419, 2026).
iron deficiency (3 papers, 2020 to 2025). "As shown in this study, during a 7-day period, increased SF levels are associated with a decrease in RET-He and Delta-He values, further highlighting SF limited utility in diagnosing iron deficiency in critically ill patients." (PMID 40270491, 2025). "We could show that both RET-He and Delta-He indeed have considerable use both in absolute iron deficiency and in FID." (PMID 36611936, 2022). "Especially RET-He demonstrated a particularly strong specificity for both types of iron deficiency." (PMID 36611936, 2022).
liver cancer (3 papers, 2016 to 2021). An epithelial or non-epithelial malignant neoplasm that arises from the liver. "Sorafenib, also approved for several indications including kidney and liver cancer, has demonstrated preclinical activity in RET models but has yet to be tested in patients selected based on RET fusion status." (PMID 27429741, 2016). "Interestingly, we found that most of these key node genes play important roles in tumorigenesis (RET, CEACAM5), immune regulation (CTSG, CD79A) and the EMT pathway (COL10A1, COL11A2), suggesting their significant role in the recurrence of liver cancer." (PMID 34956309, 2021).
lung carcinoid tumor (3 papers, 2022 to 2025). A neuroendocrine neoplasm that arises from the lung. "In NETs, including a subset of GEP-NETs, RET mutations or fusions have been implicated in tumorigenesis, including in a case report of successful administration of selpercatinib (a selective RET inhibitor) in a patient with a RET-fusion lung carcinoid tumor." (PMID 41303577, 2025).
lymphoid neoplasm (3 papers, 2015 to 2023). A neoplasm composed of a lymphocytic cell population which is usually malignant (clonal) by molecular genetic and/or immunophenotypic analysis. "Among the entire COSMIC dataset of 18 163 tumour samples with available RET genotypes, only one (a lymphoid neoplasm, ID: COSM1159820) presented the RET Y791F variant (0.002% – no information available regarding somatic or germline status)." (PMID 25425582, 2015).
parathyroid carcinoma (3 papers, 2022 to 2025). "Genetic variants associated with parathyroid cancer and familial PHPT have been reported, and MEN1, CDC73, and RET mutations are known to be associated with the pathogenesis of parathyroid cancer or familial PHPT." (PMID 35586626, 2022).
pericardial effusion (3 papers, 2023 to 2025). Fluid collection within the pericardial sac, usually due to inflammation. "A common side effect of selective RET inhibitors is the occurrence or worsening of edema, including peripheral, facial, eyelid, and other generalized presentations (as pleural/pericardial effusions and ascites)." (PMID 38118420, 2023).
pneumonia (3 papers, 2023 to 2024). An acute, acute and chronic, or chronic inflammation focally or diffusely affecting the lung parenchyma, caused by an infection in one or both of the lungs (by bacteria, viruses, fungi, or mycoplasma.). "Pneumonia is a AE of RET inhibitor; it is also one of the cause of dose modification, interruption, and discontinuation." (PMID 39372206, 2024). "The cause of pneumonia induced by pralsetinib is currently unknown and may be related to the downstream pathway of RET gene." (PMID 37924363, 2023). "We also observed an earlier onset of pneumonia within 1–3 months after receiving RET‐TKI compared with 6 months in the previous study." (PMID 38349001, 2024). "RET fusion-positive advanced NSCLC patients who developed pneumonia during pralsetinib treatment from January 2020 to December 2022 were included." (PMID 37924363, 2023). "A total of 8 patients with pneumonia were included in the study, most of which were non-smoking female patients and the main fusion gene was KIF5B (87.5%), which was consistent with the general characteristics of RET fusion population." (PMID 37924363, 2023).
rectal cancer (3 papers, 2021 to 2025). A primary or metastatic malignant neoplasm that affects the rectum. "Fusions appeared to be more common in colo-rectal cancers with RET (CCDC6-RET), ALK (EMl4-ALK) and multiple fusions (RAF1, BRAF, and FGFR3) than in NSCLC patients, but larger studies are necessary to confirm this tendency." (PMID 35267628, 2022). "This was in concordance with previous studies, demonstrating the significant downregulation of RET during colon and rectal cancers." (PMID 33906292, 2021). "In the integrated analysis of genome-wide DNA methylation and gene expression profiling study, RET was the second of nine potential biomarkers that was introduced for the rectal cancer." (PMID 33906292, 2021). "NTRK alterations (NTRK1/2/3) were present in 0.9% and 0.5%, ROS1 alterations in 0.4% and 0.2%, RET alterations in 0.6% and 0.4%, and ALK alterations in 0.5% and 0.4% of samples in colon and rectal cancer, respectively." (PMID 39865537, 2025).
renal carcinoma (3 papers, 2014 to 2021). A carcinoma arising from the epithelium of the renal parenchyma or the renal pelvis. "To test whether this interaction was dependent upon RET activation, we employed Sorafenib, a multikinase inhibitor, which inhibits RET and is being used to currently treat RET-driven renal cancers." (PMID 24466333, 2014).
Ascites (2 papers, 2023 to 2024). Accumulation of fluid in the peritoneal cavity (between the layers of the peritoneum that lines the abdomen). "In a study, it was discovered that approximately 7% of patients in the selpercatinib group experienced chylous ascites due to selective RET inhibitors, whereas no AEs were observed in the pralsetinib group." (PMID 39372206, 2024).
astrocytoma (2 papers, 2019 to 2022). "It has been reported that the mRNA levels of RET are elevated in astrocytoma patients with IDH mutations, who are known to have prolonged survival." (PMID 31620163, 2019). "Several of the fusions detected that, to our knowledge, have not been previously reported in CNS tumors included PDGFRA-SCAF11 as well as 2 RET fusions, RET-CCDC6 and RET-PCM1, all of which occurred in cases of IDH-wildtype infiltrating astrocytoma." (PMID 36397144, 2022).
ataxia telangiectasia (2 papers, 2016 to 2018). Ataxia-telangiectasia is the association of severe combined immunodeficiency (affecting mainly the humoral immune response) with progressive cerebellar ataxia. "WSE correlated with mutations in the genes SMARCB1 (p=0.002), Ataxia telangiectasia mutated (p=0.004), Kinase Insert Domain Receptor (p=0.006), and were borderline significant in RET and EGFR exon." (PMID 30093964, 2018).
autoimmune disease (2 papers, 2023 to 2025). A disorder resulting from loss of function or tissue destruction of an organ or multiple organs, arising from humoral or cellular immune responses of the individual to their own tissue constituents. "PTC is often associated with organ-specific autoimmune diseases, such as HT, and RET/PTC, RAS, or BRAF activate a transcriptional program in inflammatory thyrocytes." (PMID 37959281, 2023).
carcinoid (2 papers, 2021). "In another carcinoid-study, carcinoids showed MEN1 gene alterations, resulting in failures of chromatin remodeling, while LCNEC were characterized by mutations in DNA repair genes (loss of orthopedia homeobox) and upregulation of the RET gene." (PMID 34307132, 2021).
chronic myelomonocytic leukaemia (2 papers, 2013 to 2019). "Finally, we detected substantial levels of RET receptor on THP1 cell, a monocytic leukemia cell line also known to produce remarkable amount of RET transcript, although at intermediate level if compared with our negative (IMR-32 and SK-N-MC cell lines) and positive (MTC-TT cell line) controls." (PMID 23527089, 2013).
cognitive disorder (2 papers, 2017 to 2024). A disease affects cognitive processes. "Abnormalities in the structure and signaling of GFRα1 (GFRA1 gene) or RET (RET gene), caused by genomic variants or mutations within these genes, may also underlie various mental and cognitive disorders." (PMID 38646100, 2024).
emphysema (2 papers, 2020 to 2021). "However, unlike bevacizumab, SU5416 blocks VEGF receptors, platelet derived growth factor (PDGF) receptor, c - Kit (stem cell factor receptor), and RET (tyrosine kinase receptor), not VEGF itself, causes emphysema as well as pulmonary hypertension." (PMID 34333902, 2021).
Fraser syndrome (2 papers, 2017 to 2020). Fraser syndrome is a rare clinical entity including as main characteristics cryptophthalmos and syndactyly. "Of the candidate genes, four genes (i.e., ITGA8, GRIP1, FREM1, and FREM2) were Fraser syndrome-related genes, encoding proteins that functionally converged on the glial cell-derived neurotrophic factor/RET/bone morphogenic protein (BMP) signaling pathways." (PMID 29197384, 2017).
head and neck squamous cell carcinoma (2 papers, 2022 to 2024). A squamous cell carcinoma that arises from any of the following anatomic sites: lip and oral cavity, nasal cavity, paranasal sinuses, pharynx, larynx, and salivary glands. "Other cancer types, such as STAD, LUSC, LUAD, head and neck squamous cell carcinoma (HNSC) and PCPG, also exhibited dominant RET mutations although they had much lower rate of RET alterations." (PMID 35978072, 2022).
Huntington disease (2 papers, 2019 to 2023). Huntington disease (HD) is a rare neurodegenerative disorder of the central nervous system characterized by unwanted choreatic movements, behavioral and psychiatric disturbances and dementia. "These genes, RET and PLK5, play a significant role in movement-related functions, but their expression is downregulated in Huntington’s disease (HD)." (PMID 37761940, 2023).
immune deficiency (2 papers, 2021 to 2025). "Results of Western blotting showed that BYS10 dose-dependently degraded RET protein levels in the Ba/F3-KIF5B-RET-V804L xenograft model with immune deficiency and significantly inhibited the phosphorylation of RET kinase in tumor tissues." (PMID 41181595, 2025).
intestinal tumors (2 papers, 2022). "Moreover, ZD6474-treated mice had significantly fewer small intestinal tumours, demonstrating the functional requirement of VEGFR, RET, and EGFR activity for the optimal growth of intestinal tumours with activated TGFβ/ALK5 signalling." (PMID 36477656, 2022).
medullary sponge kidney (2 papers, 2018 to 2023). Medullary sponge kidney (MSK) is a birth defect of the tubules - tiny tubes inside the kidneys. "This case report highlights the coexistence of these two conditions associated with RET polymorphism, which contributes toward the understanding of the pathogenesis of medullary sponge kidney." (PMID 29983117, 2018).
myocardial infarction (2 papers, 2011 to 2023). Gross necrosis of the myocardium, as a result of interruption of the blood supply to the area, as in coronary thrombosis. "We identified seven CNV regions that were associated significantly with hyperlipidemia and myocardial infarction in our patients through multistage analysis (P<0.001), at 1p21.3, 1q31.2 (CDC73), 1q42.2 (DISC1), 3p21.31 (CDCP1), 10q11.21 (RET) 12p12.3 (PIK3C2G) and 16q23.3 (CDH13), respectively." (PMID 22369086, 2011).
Opportunistic infection (2 papers, 2023 to 2024). An infection that is caused by a pathogen that would generally not be able to cause an infection in a host with a normal immune system. "Therefore, pralsetinib may affect cellular immunity by inhibiting the RET downstream pathway and the function of T cells and NK cells, leading to increased risk of infection, especially opportunistic infection." (PMID 37924363, 2023).
pancreatic neuroendocrine tumor (2 papers, 2025). Pancreatic endocrine tumor, also known as pancreatic neuroendocrine tumor (PNET), describes a group of endocrine tumors originating in the pancreas that are usually indolent and benign, but may have the potential to be malignant. "Nonetheless, late-onset manifestations of MEN1, such as asymptomatic pancreatic neuroendocrine tumors in patients over 70 years old, have been documented, and low-penetrance RET mutations (e.g., K666N) have been associated with delayed MEN2 diagnoses and milder phenotypes." (PMID 40525079, 2025).
Pleural effusion (2 papers, 2022). The presence of an excessive amount of fluid in the pleural cavity. "Our case also showed that pleural effusion supernatant is an alternative liquid biopsy specimen for detecting rare RET fusion genes." (PMID 36451418, 2022). "It is noteworthy that we were able to detect RET fusion by extracting RNA from 7-year-old pleural effusion cell blocks, which contained a low percentage of malignant cells." (PMID 36452495, 2022). "We could further confirm RET from formalin-fixed paraffin-embedded (FFPE) specimens from 7-year-old pleural effusion cell blocks, which were morphologically similar to re-biopsy sample in terms of malignant cells with large nucleoli." (PMID 36452495, 2022). "In addition, we were able to confirm RET from FFPE specimens obtained from 7-year-old pleural effusion cell blocks." (PMID 36452495, 2022).
psychosis (2 papers, 2022 to 2023). "Our results suggest a potential mechanism as to how methamphetamine elicits individual psychosis risk in young adults—variation in initial striatal GDNF induction and subsequent GFRα1 and RET downregulation may determine individual susceptibility to psychosis." (PMID 37759827, 2023). "This is important, as the observed dual effect suggests a mechanism as to how methamphetamine induces psychosis with incomplete penetrance—individuals with higher GDNF induction and less prominent GFRa1/RET downregulation are more likely to develop psychosis." (PMID 37759827, 2023). "Our results may guide future experiments and precision medicine development for methamphetamine-induced psychosis using GDNF/GFRa1/RET antagonists." (PMID 37759827, 2023). "In that regard, first episode psychosis patients with high levels of GDNF in the CSF may be of special interest for future research on A2AR and RET inhibition therapy." (PMID 35618883, 2022).